CD44 (CD44 molecule (IN blood group))
Diseases named in the same sentence as CD44 in open-access papers (continued):
Sharing a sentence is not in itself a finding about the gene and the disease.
cancer (continued). "The flow cytometry analysisof ASCs revealed that more than 90% of all cancer andnormal ASCs were positive for the stem cell specificmarkers, including CD90, CD105, CD44 and CD73, butthey were negative for the expression of hematopoieticspecific markers, such as CD45, CD34 and CD14." (PMID 31721539, 2020). "Cell morphology and p-MLC2 levels were assessed as amoeboid markers; ki-67 staining as a proliferative marker; WNT11, WNT5B and DAAM1 expression as non-canonical Wnt markers; and ALDH1A1, ALDH1A3, CD44, NANOG and OCT4 were evaluated as cancer stem cell-related markers." (PMID 33082334, 2020). "Despite the limitations, our study indicated for the first time that unlike other anti-cancer drugs, FTD might be effective against CSC-like cells expressing high levels of CD44 and CD133." (PMID 31619711, 2019). "CD44+/CD24-/low stem cell/progenitor cells were isolated from normal and immortalised mammary cells (HMEC and MCF10A, respectively), LUM (MCF-7, HCC1428), HER2-E (MDA-MB-468, HCC1954) and TN (BT549, Hs578T and MDA-MB-231) cancer cells." (PMID 28202042, 2017). "We found that MMP-2 decreased by inhibiting CD44 via blocking mTOR signaling, whereas MMP-9 was not, demonstrating that the MMPs may have diverse roles in the signaling pathways of various cancers." (PMID 26202311, 2015). "Recently it has been pointed out that long-term infection by P. gingivalis of oral cancer cells induces an increase in the expression level of CD44 and CD133, well-known cancer stem cell markers, and promotes the tumorigenic properties of infected cancer cells compared to non-infected controls." (PMID 26635767, 2015). "However, including CD44 and CD24, no marker can be used universally to identify CSCs in various cancers." (PMID 22693526, 2012). "Thus, at sites of metastasis, cancer cell phenotype based on CD44 and CD24 expression does not change significantly compared with that of parental cancer cells." (PMID 17062128, 2006). "One study separated CSCs with single-cell assay of human LUAD cancer cells (A549), with CD44+/CD24−/phenotype characteristics, special stemness-related gene expression, and Hoechst 33342 dye efflux assay, and the secondary protein structure of CSCs changed when compared to non-stem cancer cells." (PMID 34745015, 2021). "However, the JNK or JAK2 inhibitor could neither augment the anti-cancer effects of pKAL on STAT3 activity, nor on the expressions of CD44, Oct 3/4, β-catenin, and MMP-9 of RT-R-MDA-MB-231 cells." (PMID 32326231, 2020). "In addition, DENSpm-treated cells exhibited elevated levels of expression of several key stem cell markers including POU5F1, Sox9, CD44, BMI1, and Lin28B, although other transcripts that are found in liver stem and cancer stem cells remained absent (PROM1, CD133)." (PMID 30567412, 2018). "BCSCs (CD24− CD44+ ESA+) isolated from MCF10DCIS.com cells, which give rise to ductal carcinoma in situ, exhibit higher expression levels of lipogenic genes such as ATP citrate lyase (ACLY), acetyl CoA carboxylase 1 (ACC1), and FASN compared to non-stem cancer cells." (PMID 29907133, 2018). "Interestingly, elevated levels of endogenous GAS6 were identified in putative cancer stem cells (CSCs, CD133+/CD44+) compared to non-CSCs (CD133–/CD44–) isolated from PCa/osteoblast cocultures in vitro and in DTCs isolated from the bone marrow 24 hours after intracardiac injection." (PMID 27028863, 2016). "Furthermore, systematic characterization for multiple single cell-derived clones and negative enrichment of CD44+/ESA+ stem-like cancer cells, all of which recapitulate stem-like cancer characteristics, suggest stochastic adaptation rather than selection of pre-existing subclones." (PMID 26136078, 2015). "Finally, ESA+/CD24−/low/CD44+ cancer stem cells from RB-negative TNBC lines were consistently more sensitive to gamma-irradiation than RB-positive lines, whereas the effect of chemotherapy on the cancer stem cell fraction varied irrespective of RB1 expression." (PMID 24265703, 2013).
cancer (continued). "The CD24neg subpopulation within CD44+CD24neg/low cells showed no Notch1 activation and was GSI insensitive both in 3D (spheres and soft agar colonies) and in xenografts, highlighting important therapeutic implications of heterogeneity in cancer stem cell populations." (PMID 23982961, 2013).
infection (339 papers, 2007 to 2026). The state of being infected such as from the introduction of a foreign agent such as serum, vaccine, antigenic substance or organism. "Mice deficient in CD44 exhibited reduced early mucosal hyperplasia and leukocyte recruitment, followed by delayed resolution of infection and persistent inflammation." (PMID 31226944, 2019). "More direct evidence of CD44’s involvement in OM was provided by the response of CD44-deficient animals to NTHi infection of the ME." (PMID 31226944, 2019). "Here we have revealed a previously unrecognized function of such CD44 in virus spread; CD44 on virus particles interacts with CD44 on FRCs via virus-associated HA, which leads to virus capture and subsequent trans-infection mediated by FRCs." (PMID 29934525, 2018). "Here, we report that in mice infected with a mouse-adapted strain of SARS-CoV-2, treatment with a combination of two anti-CD44 monoclonal antibodies confers a significant survival benefit and reduces weight loss and clinical score of the mice on Day 4 post infection." (PMID 41279061, 2025). "The present study explored the increased vascular endothelial permeability caused by GPS infection, and the potential mechanism by which Lut could counteract this phenomenon via the CD44 signaling pathway in porcine iliac artery endothelial cells (PIECs)." (PMID 40868017, 2025). "Functional analysis showed that LAG3-expressing CD4+CD44+ T cells secreted elevated levels of interleukin-4 (IL-4) and IL-10 at 2 and 4 weeks post-infection." (PMID 41680821, 2026). "To visualize the effects of anti-CD44 treatment on localization of HA and immune cells in the infected lung, we performed immunofluorescence (IF) on samples from day 4 post-infection." (PMID 41279061, 2025). "One of CD44’s critical functions is its participation in the infection and propagation of pathogens." (PMID 40544280, 2025). "Similar to the spleen, USUV infection led to an increase in the number of neutrophils in the blood, which was observed in both CD44- and CD44+ populations, with CD44+ neutrophils representing the largest neutrophil population in the blood." (PMID 41472308, 2025). "Albumin, a known marker of lung damage, was measured in bronchoalveolar lavage fluid (BALF) day 4 of infection and was decreased following anti-CD44 treatment." (PMID 41279061, 2025). "This suggests that CD44 expression in macrophages increased at 60 min post-infection after 24 h of RA pretreatment, indicating that RA treatment enhanced the time-dependent expression of adhesion molecules on the macrophage surface." (PMID 40370796, 2025). "Overall, the results of the present study demonstrate that GPS infection of PIECs activates the CD44 signaling pathway to increase vascular endothelial permeability and that these effects can be significantly inhibited by Lut." (PMID 40868017, 2025). "It is also possible that anti-CD44 treatment blocks neutrophil migration into the lungs during infection." (PMID 41279061, 2025). "Phenotypic assessment of Tbet+ cells after neonatal and adult infection showed most cells were in the effector state (eg CD44+CD62L–), while neonatal GATA3+ cells were less likely to be activated." (PMID 40280180, 2025). "In contrast, infection of CoMtb mice induced an increased representation of activated CD4 T cells (primarily defined by CD44 and IFNg) and MDCs at early time points (d17), and this was correlated with decreased bacterial burdens at this time point." (PMID 40736456, 2025). "Tem cells (CD44+ CD62L−, gated on CD4+ FOXP3+) were increased by MNV infection in Ncf190H mice, whereas naive Tregs (CD44− CD62L+, gated on CD4+ FOXP3+) and Tcm/ Tvm cells (CD62L+ CD44+, gated on CD4+ FOXP3+) were decreased." (PMID 39939342, 2025). "Lut alleviated the increase in vascular endothelial permeability during GPS infection by inhibiting the CD44 signaling pathway." (PMID 40868017, 2025).
infection (continued). "CD44 is the primary HA receptor, but other HA receptors exist and can have roles in the immune response to infection." (PMID 41279061, 2025). "The frequencies and numbers of activated (CD44+) tetramer+ T cells were at least 10 times higher in vaccinated mice compared with unvaccinated mice at post-infection day 5 or 6 after infection with H. capsulatum or C. posadasii, respectively." (PMID 41061037, 2025). "Volcano plots revealed that the most highly upregulated genes in response to OC43 infection, such as SOD2, CD44, STAT1 and MX1, were inflammation-associated genes and antiviral ISGs." (PMID 40368896, 2025). "Data disclose that CD14 and CD44 are weakly expressed by hemocytes under basal conditions and thus their expression is inducible and modulated by infection." (PMID 38191588, 2024). "As done for GPNMB, we determined CD44 function in vivo using anti-CD44 mAb treatment in the SeV mouse model with dosing at 5–14 days after infection." (PMID 39052353, 2024). "qPCR and western blot results indicated that the mRNA and protein levels of CD44 were considerably downregulated in MNNG HOS cells after shPOLE2 lentivirus infection." (PMID 38627379, 2024). "The qRT-PCR results revealed that the SPP1 expression and CD44 increased in the liver at 6 w after infection." (PMID 39590301, 2024). "At one week post infection, we observed a significant increase in the percentage of activated (CD44+) CD4+ T cells in μMT mice." (PMID 37721965, 2023). "It is noteworthy that, while CD28 is a costimulatory receptor expressed on activated T cells, CD44 is an adhesion receptor involved in activated T cell migration between lymphoid tissues and sites of infection." (PMID 37896880, 2023). "Similar to our findings in μMT mice, by two weeks post infection co-transfer of B cells enhanced FoxP3 expression and diminished T-bet expression on CD44+CD4+ T cells." (PMID 37721965, 2023). "It is noteworthy here that CD44 is an activation adhesion receptor involved in the T cell migration between the lymphoid tissues and site of infection." (PMID 36851171, 2023). "μMT mice also displayed ~30% increase in T-bet expression on CD44+CD4+ T cells one week post infection, though this difference dissipated two weeks post challenge." (PMID 37721965, 2023). "At day 10 (effector) and day 30 (memory) post-infection, scRNA-seq and scATAC-seq were performed on KO and WT OT-I cells isolated from recipient spleens and labeled with Total-seq antibodies to CD44, CD62L, CD127, and KLRG1." (PMID 37414528, 2023). "Infection of NPC cells with EBV can increase the CD44-positive population, which shows enhanced tumorigenicity and chemoresistance compared with the CD44-negative population." (PMID 37762374, 2023). "FMT from l-arginine-treated mice caused significant increases in IFN-γ-producing CD4+CD44+ T cell and CD4+CD44+ T cell populations in the cervical lymph nodes compared to control mice during Mabc infection." (PMID 35579969, 2022). "In contrast, there was a significant reduction in the percentage of Adrb2-/- CD62L+/CD44- (central memory-like) cells at d14 post-infection." (PMID 35944008, 2022). "The proliferation (Ki67), exhaustion (PD1), and activation (CD44) markers were increased many folds in splenic CD8+ T cells upon infection, comparable between both groups of mice." (PMID 36105746, 2022). "In the present study, deterioration of clinical signs during TMEV infection was accompanied by a significant reduction of CD44 positive area in the lesioned ventral part of astrocyte depleted mice compared to all control groups." (PMID 35714111, 2022). "In this study, it seems to Ad-null infection slightly caused the upregulation of β-catenin, CD133, and CD44 in rat HCC." (PMID 36055405, 2022). "Flow cytometric analysis after polyclonal stimulation with anti-CD3/CD28 showed that the H1-DDA/TDB-induced accumulation of IL-17A-producing cells within the CD44+CD4+CD90+ population at week 2 post-infection was highly impaired in IL-23p19−/− mice." (PMID 34351501, 2021).
infection (continued). "After neutrophils perform their functions at the site of infection, they get removed by macrophages, and CD44 serves as an apoptotic signal for the macrophages." (PMID 34235202, 2021). "Blockade of CD44 from days 1–4 after infection resulted in improved clinical survival and clinical scores." (PMID 34185704, 2021). "The frequency of CXCR5+ PD1+ Tfh cells among the CD19−CD4+ CD44+ cells was also significantly reduced in lymph nodes of Tslpr-/- mice on day 10 post-infection compared with WT mice." (PMID 34659250, 2021). "We demonstrated that virion-incorporated CD44 is necessary for the trans-infection of HIV-1 mediated, by a secondary lymphoid organ (SLO) fibroblastic reticular cell (FRC)." (PMID 34696365, 2021). "We found that TH1 (CD4+ CD44+ FoxP3- Tbet+) cells were the predominant CD4 T-cell subset during UgCl233 infection, ranging from 20% - 48% of activated CD4 T-cells." (PMID 35186781, 2021). "Virion-incorporated CD44 facilitates the FRC-mediated trans-infection of HIV-1 via interactions with HA in tissue culture." (PMID 34696365, 2021). "At day 8 after infection, we found that the frequencies and numbers of total and effector (CD44+ CD62L-) CD4+ T cells derived from Ddb1-TaKO (CD45.1+ CD45.2+) BM was much lower compared with that derived from WT (CD45.2+) BM." (PMID 34526995, 2021). "Cell-surface glycoprotein CD44 (an adhesion receptor) was labeled red under fluorescence and its expression in infected cells was increased by 9 fold at 4 h post-infection compared to uninfected HBMEC." (PMID 34163451, 2021). "Most brain T cells showed a TEM phenotype (Cd44+CD62L-KLRG1-) with low effector functions but with the capacity to proliferate since the early stage of infection." (PMID 34587172, 2021). "On d70 post infection, despite unaltered total cell counts in the spleen, we detected a relative as many as a threefold increase in Nr2f6-deficient CD8+CD44+OVAtet+ cells." (PMID 33589606, 2021). "At 12 or 24 h after infection, the abundances of CD44 and PAI-1 were nearly 2-fold higher than those of the controls." (PMID 34515624, 2021). "Upon analysis of the lung at 14 days post-infection, activation markers CD11a and CD44 were both upregulated on polyclonal CD4+ T cells." (PMID 34237106, 2021). "To do so, we performed SCENIC analysis on GP33+ CD44+ CD8+ T cells from siIELs 30 days post-LCMV-ARM infection." (PMID 34440912, 2021). "A significant increase in the proportion of cytokine-producing CD4+ Tem (CD44+CD62L−) in spleens after the protein stimulation was observed in all vaccinated groups of animals compared to infection control." (PMID 34835204, 2021). "These T cells all expressed CXCR3 as the infection progressed, and exhibited an activated CD44+CD62L− profile by day 7 p.i.." (PMID 34707143, 2021). "In this study, we observed significantly increased PEDV replication in CD44-knockdown Vero E6 cells, and infection of CD44-overexpressing Vero E6 cells with PEDV was significantly inhibited." (PMID 34515624, 2021). "The robust upregulation of the CD44 gene during infections supports its involvement in both pathogenesis and recovery." (PMID 32349323, 2020). "The CD44 can be induced in T cells upon monocyte activation by inflammatory stimuli; moreover, an upregulation of the CD44 gene was observed during infections, supporting its possible involvement in both pathogenesis and recovery processes." (PMID 32349323, 2020). "Since memory T cell responses are critical to induce long-term protection against infection, the LiChimera-specific CD4+ and CD8+ T cells were also evaluated for expression of markers associated with memory cells, i.e., CD44 and CD62L." (PMID 32629975, 2020). "Extravascular CD8+ cells were predominantly CD44+CD62L−CD69+CX3CR1− consistent with the phenotype of BTRM reported in other infection models." (PMID 32878636, 2020).